ATG4B (autophagy related 4B cysteine peptidase)
Diseases named in the same sentence as ATG4B in open-access papers (continued):
Sharing a sentence is not in itself a finding about the gene and the disease.
Hyperglycemia (5 papers, 2017 to 2024). An increased concentration of glucose in the blood. "In this study, it was demonstrated that AIF-1 regulated the levels of miR-34a, ATG4B, autophagy, inflammation, and oxidative stress in glomerular endothelial cells induced by hyperglycemia via in vivo and in vitro studies." (PMID 36345369, 2022). "ATG4B is modified via S-nitrosylation, resulting in the impairment of autophagy and further neurotoxicity in response to hyperglycemia." (PMID 35456009, 2022). "Therefore, ATG4B S-nitrosylation-induced autophagic inhibition increases neurotoxicity and hyperglycemia." (PMID 35456009, 2022). "One possibility is that during chronic hyperglycemia, sustained TXNIP expression and ROS/RNS stress prevail under mitochondrial damage, which may cause a reduction of the delipidating activity of ATG4B on LC3BII." (PMID 28492550, 2017). "Moreover, NO-mediated S-nitrosylation of ATG4B induced autophagic impairment and neurotoxicity in response to hyperglycemia, thus, the S-nitrosylation of autophagy pathway members may represent a new autophagic regulatory mechanism under oxidative stress." (PMID 38455652, 2024). "Consistent with our analysis, GABARAPL1 and 2 activity was processed by ATG4B, whereas the ATG8 family except GABARAPL1 was inhibited by the inactivity of ATG4B, resulting in neurotoxicity induced by hyperglycemia." (PMID 32685442, 2020).
melanoma (4 papers, 2019 to 2025). A malignant, usually aggressive tumor composed of atypical, neoplastic melanocytes. "In exploring the effects of autophagy inhibition on MHC-I expression, we employed B16-Atg4bC74A melanoma cells engineered to express a mutant form of Atg4b, which blocks autophagy when induced by doxycycline (Dox)." (PMID 40016522, 2025). "Among them, we found several autophagy-related genes such as AMBRA1, ATG5, ATG12, ATG13 and ATG4B, which could be potentially downregulated in BRAFi-resistant melanoma cells." (PMID 30254376, 2019). "Our findings confirm this hypothesis, showing that autophagy inhibition raises MHC-I protein levels on melanoma cells, and further increases in MHC-I expression are not observed with Ber treatment following Atg4b mutation." (PMID 39329721, 2024).
Obesity (4 papers, 2017 to 2021). Accumulation of substantial excess body fat. "In plasma, atg4b−/− mice showed an increase in the circulating levels of many amino acids, normally associated with metabolic disturbances and obesity." (PMID 34436422, 2021). "Atg4b-deficient mice, which show limited autophagic competence, exhibit a major increase in body weight in response to distinct obesity-associated metabolic challenges." (PMID 28771229, 2017). "To understand the cause of the obesity-linked alterations observed in Atg4b-deficient mice, we examined daily food intake and energy expenditure by means of the Oxymax/CLAMS system." (PMID 28771229, 2017). "Altogether, these data show that the partial and systemic autophagy defect of Atg4b-null mice not only predisposes to diet-induced obesity, but also renders them more prone to pancreatic β-cell damage, also predisposing them to environmentally induced type-I diabetes." (PMID 28771229, 2017). "Thus, increased meta-inflammation is likely not a major cause for the higher obesity observed in autophagy-deficient mice, which may be mainly linked to the reduced autophagic flux that atg4b−/− mice manifest in all tissues, including liver and white fat." (PMID 28771229, 2017).
diabetes (3 papers, 2017 to 2024). "Research indicated that ATG4B deficiency mice are viable and fertile, but these mice are susceptible to many diseases, including diabetes, muscle atrophy and myocardial damage which suggests that targeting ATG4B directly is not a satisfactory choice." (PMID 38803355, 2024).
liver cancer (3 papers, 2017 to 2023). An epithelial or non-epithelial malignant neoplasm that arises from the liver. "Importantly, only a few genes were previously implicated with liver cancer development (ATG4B, CCR5, MCM6, and UCN), whereas most of the epidrivers were newly identified." (PMID 34375307, 2021). "SMAD2 and SMAD3 correlated with autophagy-related scores (based on ATG12, ATG7, ATG3, ATG5, ATG4B, PIK3C3, PRKAA2, and GABARAPL1) in liver cancer." (PMID 37790613, 2023).
lung fibrosis (3 papers, 2018 to 2022). "In an autophagy-impaired mouse model, Atg4b-deficient mice were treated with bleomycin to induce pulmonary fibrosis." (PMID 32082178, 2019). "We also showed that compromised autophagy in lungs from Atg4b null mice is associated with exacerbated lung damage, epithelial apoptosis and the development of lung fibrosis at 21 days after tunicamycin treatment." (PMID 30147026, 2018). "We propose that our Atg4b deficient model mimics a pathogenic scenario in which lung fibrosis is favored by aging associated drivers such as abnormal autophagy and ER stress." (PMID 30147026, 2018). "ATG4b-deficient mice displayed that autophagy disruption contributed to BLM-induced lung fibrosis." (PMID 36386240, 2022). "Our findings indicate that ATG4B protein and autophagy are essential to mitigate ER stress and to prevent tunicamycin-induced epithelial apoptosis and lung fibrosis." (PMID 30147026, 2018). "Moreover, we have shown that mice deficient in the cysteine-protease ATG4B, which exhibit a decrease of basal and induced autophagy, are more susceptible to bleomycin-induced lung injury and fibrosis, upholding the protective role for autophagy activity and ATG4B in the development of lung fibrosis." (PMID 30147026, 2018). "Using the Atg4b-deficient mice as a model, that partially reproduces the autophagy deficient conditions reported in aging and IPF lungs, we show for the first time how autophagy impairment and ER stress induction, contribute simultaneously to development of lung fibrosis in vivo." (PMID 30147026, 2018).
pancreatic ductal adenocarcinoma (3 papers, 2019 to 2025). An infiltrating adenocarcinoma that arises from the epithelial cells of the pancreas. "The high expression of ATG4B has been correlated with shorter survival in patients with pancreatic ductal adenocarcinoma (PDAC)." (PMID 40883962, 2025).
acute kidney injury (2 papers, 2022). Sudden and sustained deterioration of the kidney function characterized by decreased glomerular filtration rate, increased serum creatinine or oliguria. "Although little is known about the role of ATG4B in DKD, miR-34a is thought to regulate autophagy by targeting ATG4B, leading to acute kidney injury." (PMID 36465646, 2022).
glaucoma (2 papers, 2023 to 2024). Increased pressure in the eyeball due to obstruction of the outflow of aqueous humor. "To determine the effects of ATG4B deficiency on RGC death in glaucoma, we quantified RGCs in the peripheral and central region of the retina in whole retinal flat mounts immunostained with anti-BRN3A antibody." (PMID 37620383, 2023). "Atg4b deficiency mitigates glaucomatous IOP elevation in the DBA/2 J mouse model, a well-established model for spontaneous glaucoma." (PMID 39882536, 2024).
leukemia (2 papers, 2025). A malignant (clonal) hematologic disorder, involving hematopoietic stem cells and characterized by the presence of primitive or atypical myeloid or lymphoid cells in the bone marrow and the blood. "Similarly, compared to WT AML model mice, ATG4B‐deficient AML model mice exhibited a markedly decreased leukemia burden and prolonged survival even after serial transplantation." (PMID 40788108, 2025). "To further investigate the function of ATG4B in leukemia progression, we inhibited ATG4B activity using an ATG4B inhibitor and gene knockdown in mouse AML cells and assessed cell proliferation." (PMID 40788108, 2025). "Lastly, we investigated the role of ATG4B in leukemia progression using AML patient‐derived xenografts (PDX)." (PMID 40788108, 2025). "Treatment with an ATG4B inhibitor significantly reduced the leukemia burden and extended the overall survival of the PDX mice." (PMID 40788108, 2025). "In this study, we demonstrated a link between an aberrant energy supply, cellular DNA repair defects, and leukemia progression by promoting the translocation of ATG4B from the cytoplasm to the nucleus." (PMID 40788108, 2025). "This suggests an autophagy‐independent role for ATG4B in the progression of MLLT3‐KMT2A‐positive leukemia." (PMID 40788108, 2025). "To investigate the role of ATG4B in leukemia progression, we examined the protein levels of ATG4B in AML cells." (PMID 40788108, 2025). "The nuclear ATG4B‐mediated DNA repair defect is significantly exacerbated within acute myeloid leukemia (AML) cells, promoting leukemia progression in an AML mouse model." (PMID 40788108, 2025). "Furthermore, we found that the nuclear ATG4B‐mediated DNA repair defect is significantly exacerbated within acute myeloid leukemia (AML) cells, promoting leukemia progression in an AML mouse model." (PMID 40788108, 2025). "However, the anti-leukemia activity of ATG4B inhibitor has not been evaluated." (PMID 41275290, 2025).
non-small cell lung carcinoma (2 papers, 2023 to 2025). A group of at least three distinct histological types of lung cancer, including non-small cell squamous cell carcinoma, adenocarcinoma, and large cell carcinoma. "Here, we demonstrate that an autophagy-related, ATG4B, is required for mTORC1 activity and is associated with negative clinical outcomes in non-small cell lung cancer (NSCLC)." (PMID 41065169, 2025).
acute myeloid leukemia (1 paper, 2025). Acute myeloid leukemia (AML) is a group of neoplasms arising from precursor cells committed to the myeloid cell-line differentiation. "We found that ATG4B exhibited significantly high expression levels in various acute myeloid leukemia (AML) with diverse molecular subgroups (e.g., MLL‐rearrangement, FLT3‐ITD mutation, and NPM1 mutation, etc.)." (PMID 40788108, 2025). "Importantly, it is shown that ATG4B‐mediated DNA repair defects are significantly enhanced in patient‐derived acute myeloid leukemia (AML) cells and in mouse AML cells induced by MLLT3‐KMT2A overexpression." (PMID 40788108, 2025).
asthma (1 paper, 2026). "This is the first evidence of an association with variants in ATG4B with asthma which provides a novel potential for future drug development." (PMID 41929293, 2026).
astrocytoma (1 paper, 2023). "Similarly, in the context of the IDH mutant astrocytoma, the tumor with higher AUP1 was significantly correlated with PI3K-AKT-MTOR pathway (EGFR, PDGFRA, TSC2, MTOR), and autophagy signaling (ATG4B)." (PMID 37029364, 2023).
bladder cancer (1 paper, 2021). "When tested as individual gene, 9 genes from the 11-ARG signature (APOL1, ATG4B, CASP3, ITGA3, P4HB, PRKCD, ULK2, and WDR45) exhibited a significant association between mRNA expression levels and overall survival of bladder cancer patients." (PMID 33925460, 2021). "While higher expression of APOL1, ATG4B, ITGA3, WDR45, CASP3, and PRKCD is associated with favorable survival in human bladder cancer patients, increased ULK2 and P4HB mRNA levels are negatively correlated to overall survival of bladder cancer patients." (PMID 33925460, 2021).
cardiomyopathies (1 paper, 2021). "ATG4B deficiency leads to metabolic changes that increase the levels of several nitrogenous bases and nucleosides that are often observed either in cardiomyopathies or upon cardiac damage in laboratory rodents." (PMID 34436422, 2021).
cervical cancer (1 paper, 2022). A primary or metastatic malignant neoplasm involving the cervix. "THP triggered downregulation of miR-34c-5p, which was associated with the upregulation of ATG4B and autophagy induction; conversely, overexpression of miR-34c-5p decreased ATG4B levels and attenuated autophagy in THP-treated cervical cancer cells." (PMID 35456001, 2022).
colitis (1 paper, 2016). Inflammation of the colon. "Furthermore, global knockout of Atg4b caused alterations in Paneth cell, including less number and small size of granules and decreased lysozyme, and Atg4b-deficient mice were more susceptible to DSS-induced colitis." (PMID 28119697, 2016).
COVID-19 (1 paper, 2024). A disease caused by infection with severe acute respiratory syndrome coronavirus 2. "Plasma ACBP concentrations positively correlated with ATG 3, ATG5 and LC3II, but negatively correlated with ATG4B, BECN1 and galectin 8 in participants with COVID-19." (PMID 39835130, 2024).
endometriosis (1 paper, 2016). The growth of functional endometrial tissue in anatomic sites outside the uterine body. "Specifically, we found that transcript levels of beclin-1, ATG5, ATG4B, and ATG2B were significantly decreased in endometriotic lesions compared with uterine horns (from endometriosis-induced mice treated with PBS)." (PMID 26775710, 2016).
gastric tumor (1 paper, 2022). "Consistently, the protein level of ATG4B was also significantly upregulated in gastric tumor tissues compared with normal tissues." (PMID 35184132, 2022).
HIV-1 infection (1 paper, 2024). The type species of lentivirus and the etiologic agent of acquired immunodeficiency syndrome (AIDS). "In addition, we confirmed that HIV-1 infection enhances cryptic exon inclusion in the FTD-ALS gene UNC13A and other genes, such as ATG4B and GSPM2, establishing a functional connection between HIV-1 infection and loss of TDP-43 function." (PMID 39242776, 2024).
infarction (1 paper, 2018). A localised pathological necrosis of tissue resulting from obstruction of the blood supply usually by a thrombus, an embolus, or vascular torsion. "qRT-PCR analysis showed increased miR-665-3p expression and decreased ATG4B mRNA expression in the intestinal infarction biopsies compared to the normal intestinal tissues." (PMID 29706629, 2018).
lung adenocarcinoma (1 paper, 2025). A carcinoma that arises from the lung and is characterized by the presence of malignant glandular epithelial cells. "Finally, we found that ATG4B expression is high in NSCLC patient tumors, is elevated in early-stage cancer, and predicts survival in lung adenocarcinoma patients." (PMID 41065169, 2025).
medullary carcinoma (1 paper, 2021). "In radiation-induced medullary carcinoma in 4W rats, the expression of Cdkn2a and Cxcr4 increased, whereas that of seven autophagy regulatory genes (Dapk1, Eif2ak3, Gaa, Hgs, Mapkl4, Mapt, and Pim2) and five autophagy machinery components (Atg4b, Atg5, Gabarapl2, Rab24, and Wipi1) decreased." (PMID 34580369, 2021).
motor neuron disease (1 paper, 2024). "To study the relevance of Atg4b and LC3ylation in motor neuron disease, we generated transgenic mice without Atg4b expression in the context of an ALS preclinical model G93A." (PMID 39305312, 2024).
myeloproliferative disease (1 paper, 2019). "Ectopic TMEM207 expression and Atg4b disruption were associated with the occurrence of myeloproliferative disease-like phenotype in the present transgenic mice." (PMID 31699801, 2019). "Although this is an interesting possibility, there remain unanswered questions concerning the role of WWOX and Atg4b in the pathogenesis of the onset of myeloproliferative disorders." (PMID 31699801, 2019). "Taken together, the exogenous expression of TMEM207 in bone marrow involving a disrupted Atg4b gene may be responsible for myeloproliferative disease characteristics observed in this study." (PMID 31699801, 2019). "Mutations in Atg4b and overexpression of TMEM207 may lead to myeloproliferative disease in the present model." (PMID 31699801, 2019). "Whereas several genetically manipulated animal models of myeloproliferative disease and Atg4b knockout mice exist, this mouse line harboring a genetic mutation in Atg4b and with overexpression of TMEM207 protein did not exist as a model of myeloproliferative disease-like phenotype until now." (PMID 31699801, 2019). "Moreover, it is likely that disrupted Atg4b expression in hematopoietic cells may be a crucial factor in myeloproliferative disease." (PMID 31699801, 2019). "In that paper, amorphous globular bodies in the neuropil of the deep cerebellar and adjacent vestibular nuclei were observed in Atg4b knockout mice, but there was no indication of myeloproliferative disease." (PMID 31699801, 2019). "This is because in previously reported Atg4b knockout mice, onset of myeloproliferative disease has not been identified." (PMID 31699801, 2019). "However, although several other genetically manipulated animal models of myeloproliferative disease and Atg4b knockout mice exist, this mouse line harboring a mutated Atg4b gene, and with overexpression of TMEM207 protein, has not been reported as a model of myeloproliferative disease to date." (PMID 31699801, 2019). "However, a mouse model in which Atg4b is disrupted and TMEM207 is overexpressed does not yet exist as a model of the myeloproliferative disease-like phenotype." (PMID 31699801, 2019).
myocardial hypertrophy (1 paper, 2020). "Moreover, we found that the expression of other key autophagy-related genes such as ULK1, Atg12, and Atg4B, was significantly upregulated at the protein level in the left ventricle of rats with exercise-induced myocardial hypertrophy, whereas SQSTM1 (a marker of reduced autophagy) was downregulated." (PMID 32140172, 2020).
nasopharyngeal carcinoma (1 paper, 2025). A carcinoma arising from the nasopharyngeal epithelium. "Diagram illustrating the modulation of autophagy initiation by a virus, focusing on the upregulation of ATG4B and ATG4D inhibiting distant metastasis in EBV-associated nasopharyngeal carcinoma." (PMID 40630202, 2025).
nematode infection (1 paper, 2025). "Several autophagy-related genes (ATG101, ATG4b, ATG8a, ATG8b, ATG8c, ATG18a, Tap46) were significantly upregulated in the cultivar 685 upon nematode infection, suggesting their involvement in enhancing resistance to M. graminicola." (PMID 40508124, 2025).
neuroblastoma (1 paper, 2014). Neuroblastoma (NB) is the most common solid, extracranial childhood tumor. "Atg4B, Atg7 and Atg9B were not detectable in CSF; however, the antibodies used detected these proteins in human SH-SY5Y neuroblastoma cell lysates (data not shown)." (PMID 24101586, 2014).
ocular hypertensive (1 paper, 2023). "ATG4B deficiency also prevented the development of glaucomatous IOP elevation in the experimental TGFβ2 ocular hypertensive model." (PMID 37620383, 2023).
oral cancer (1 paper, 2019). "On the other hand, silencing ATG4B significantly attenuated growth, migration, and invasion of oral cancer cells, suggesting ATG4B as a potential target for oral cancer therapy." (PMID 31771238, 2019). "The knockdown efficiency of siRNA against ATG4B at mRNA and protein levels in oral cancer cells was confirmed by quantitative PCR and immunoblotting." (PMID 31771238, 2019). "Thus, the detailed mechanisms of action of ATG4B affecting cell proliferation and invasion in oral cancer cells, particularly in clinical setting, requires further study." (PMID 31771238, 2019). "Further, knockdown of ATG4B reduced cell migration and invasion of oral cancer cells." (PMID 31771238, 2019). "In addition, silencing ATG4B with an antisense oligonucleotide (ASO) or small interfering RNA (siRNA) diminished cell proliferation of TW2.6 and SAS oral cancer cells." (PMID 31771238, 2019).
Parkinson disease (1 paper, 2019). A progressive degenerative disorder of the central nervous system characterized by loss of dopamine producing neurons in the substantia nigra and the presence of Lewy bodies in the substantia nigra and locus coeruleus. "HNRNPA1 is involved in protein translation, whereas ATG4B regulates AMPK signaling and energy homeostasis, and PSMC4 physically interacts with AMPK and is involved in Parkinson’s disease." (PMID 31097295, 2019).